KL (klotho)
Diseases named in the same sentence as KL in open-access papers (continued):
Sharing a sentence is not in itself a finding about the gene and the disease.
renal fibrosis (continued). "First, this is a descriptive study, and we observed the changes of Klotho level, autophagy level and renal fibrosis level at the end point of the experiments." (PMID 28848432, 2017). "Klotho appears to be an upstream regulator of renal fibrosis with functions simultaneously controlling multiple renal fibrosis-related cellular processes including pro-fibrotic cellular signaling, oxidative stress, inflammation and MTD8." (PMID 27703201, 2016). "We show that UUO-induced renal fibrosis is associated with aberrant DNMT expression, Klotho promoter hypermethylation and Klotho suppression." (PMID 27703201, 2016). "Here we explore the mechanism of Rhein anti-renal fibrosis by investigating its regulation of Klotho, a known renal anti-fibrotic protein whose suppression after renal injury reportedly involves aberrant DNA methylation." (PMID 27703201, 2016). "Our results confirmed that Klotho is an upstream inhibitor of renal fibrosis since Klotho knockdown aggravated the expression of a number of renal fibrosis-related proteins." (PMID 27703201, 2016). "In summary, the results from our studies provide direct evidence that aberrant DNMT expression and Klotho hypermethylation significantly contribute to renal fibrosis." (PMID 27703201, 2016). "Rhein treatment effectively corrects all these epigenetic alterations and consequentially attenuates pro-fibrotic protein expression and renal fibrosis in a Klotho-dependent manner." (PMID 27703201, 2016). "Further studies are needed to elucidate the utility of KL promoter methylation level as a marker to predict renal fibrosis and to explore the therapeutic efficacy of demethylating agent against the progression of fibrogenesis." (PMID 24224012, 2013). "Klotho primarily suppresses renal fibrosis through inhibition of TGF-ß1 signaling, and plays a central role in the pathogenesis of renal fibrosis in both experimental and human kidney diseases." (PMID 24693499, 2013). "Klotho supplementation inhibits renal fibrosis by suppression of fibrotic markers includings; α-smooth muscle actin, Fibronectin, Vimentin, collagen-1, MMPs." (PMID 24693499, 2013). "Indoxyl sulfate is a uremic toxin that reduces renal Klotho expression, and contributes to cell senescence and renal fibrosis." (PMID 24693499, 2013). "In addition, ginsenoside Rg1 protects against renal fibrosis by regulating the Klotho/TGF-β1/Smad signaling pathway." (PMID 40308781, 2025). "Hence, the restored expression and protein content of renal Klotho level in CKD mice by 3WJ-Kapt/anti-miR-34a in this study is considered one of the main pathways in reversing renal fibrosis and inflammation." (PMID 40514411, 2025). "Additionally, inhibiting DOT1L, a histone H3/lysine 79 methyltransferase, alleviated renal fibrosis by restoring Klotho expression." (PMID 40004457, 2025). "IS promotes CKD progression by inducing renal fibrosis, oxidative stress, and inflammation, impairing antioxidant systems in renal tubular and glomerular mesangial cells, and downregulating renal proximal tubule expression of klotho in animal models." (PMID 41007509, 2025). "Selective inhibition of HDAC3 with RGFP966 derepresses Klotho, reducing renal fibrosis and injury." (PMID 40004457, 2025). "Recently, USCs were shown to attenuate renal fibrosis via Klotho activation." (PMID 39858242, 2025). "Recent studies have shown that the administration of the uremic toxin IS suppresses the expression of klotho and promotes cell senescence and renal fibrosis. although the underlying mechanism has not been clarified." (PMID 38940381, 2024). "Klotho is considered to be a negative regulator of renal fibrosis." (PMID 39325739, 2024).
renal fibrosis (continued). "However, in the adenine CKD mouse model, the application of trichostatin A and the specific knockdown of HDAC3 facilitate PPARγ acetylation, leading to the upregulation of KLOTHO protein and the concurrent inhibition of renal fibrosis." (PMID 38929505, 2024). "Similarly, it has been reported that inhibition of HDAC3 and HDAC8 derepressed klotho expression during renal fibrosis." (PMID 38794880, 2024). "Finally, we investigated the effects of diminished Klotho expression on the development of renal fibrosis." (PMID 39277686, 2024). "Klotho, an anti-aging protein predominantly expressed in the kidney, particularly within renal tubular epithelial cells, is recognized as a negative regulator of renal fibrosis factors." (PMID 39325739, 2024). "A decrease in klotho levels can have a significant impact on endocrine signaling in the body, and a reduced abundance of klotho in the kidneys may directly lead to renal fibrosis and impaired renal function." (PMID 37143722, 2023). "In addition, a study found that Klotho was hypermethylated in renal fibrosis via a similar mechanism." (PMID 36864460, 2023). "Specifically, the klotho protein inhibits the binding of TGF-β1 to cell surface receptors, thereby inhibiting the TGF-β1-induced epithelial-mesenchymal transition (EMT) response, which is a crucial mechanism underlying renal fibrosis." (PMID 37143722, 2023). "Furthermore, Klotho protein inhibited renal fibrosis in a unilateral ureteral obstruction kidney-injury model." (PMID 36829798, 2023). "However, klotho can upregulate autophagy and mitigate renal cell injury and subsequent renal fibrosis." (PMID 37143722, 2023). "The upregulation of miR-34a may be involved in the feedback loop between the activation of TGF-β1 and the Klotho decrease in the progression of renal fibrosis." (PMID 37760798, 2023). "The reduction in serum and urinary sKlotho observed in the CKD groups coincided with high percentages of kidney fibrosis compared with controls, which goes in the same direction as other studies which showed that Klotho protected against renal fibrosis in mice." (PMID 36986200, 2023). "Klotho can also repress β-catenin expression and ameliorate renal fibrosis." (PMID 36059935, 2022). "Thus, the impact of ERAD on Klotho expression was also evaluated in TGF-β1-induced renal fibrosis in HK-2 cells." (PMID 35165517, 2022). "HDAC3 aberration can inhibit Klotho transcription and promote renal fibrosis." (PMID 36263180, 2022). "The protection against renal fibrosis may be related to amelioration of the downregulation of klotho in CKD." (PMID 35660779, 2022). "In addition, they inhibited the down-regulation of two renal fibrosis protective factors (klotho and BMP-7)." (PMID 36148005, 2022). "In addition, hypermethylation of these specific genes (such as RASAL1, Klotho, etc.)can also directly lead to severe renal fibrosis, suggesting that the steady-state imbalance of DNA methylation directly affects renal fibrosis progression." (PMID 36105187, 2022). "Klotho inhibition regulates fibrosis-related signaling pathways by reversing Klotho methylation, improves abnormal pathological changes in renal tissue, and slows the process of renal fibrosis." (PMID 36105187, 2022). "Klotho is a joint-regulatory gene that is involved in renal fibrosis." (PMID 36105187, 2022). "With the advantage of the pleiotropic beneficial activities, Klotho could be a novel biomarker and treatment target for renal fibrosis." (PMID 34992536, 2021). "Klotho, an anti-aging protein, reduces renal fibrosis after AKI." (PMID 34483931, 2021). "In this study, we have found that supplement of Klotho could effectively ameliorate renal fibrosis and the activation of Wnt/β‐catenin signaling." (PMID 33463897, 2021).
renal fibrosis (continued). "In addition, our recent studies demonstrated that soluble klotho deficiency in plasma is associated with albuminuria in the patients with diabetes, and serum and urinary klotho levels correlate strongly with renal fibrosis and podocyte foot process effacement." (PMID 33891667, 2021). "Additionally, Klotho downregulated early growth response factor 1 by inhibiting TGF-β1/Smad3 signaling in HG-induced human mesangial cells to combat renal fibrosis." (PMID 32774664, 2020). "Renal fibrosis, is also affected by Klotho expression levels." (PMID 32982966, 2020). "These demonstrated that Sp1 knockdown could induce renal fibrosis by downregulation of Klotho in RTECs." (PMID 32571212, 2020). "In summary, our findings show that attenuation of renal fibrosis by exogenous Klotho might be associated with depressing TGF-β1-mediated renal EndoMT, thus it may be implicated that Klotho could be developed as a target for renal fibrosis in the future." (PMID 31024315, 2019). "Intriguingly, the supplement of exogenous Klotho could alleviate renal fibrosis by inhibiting endoplasmic reticulum stress and EMT, targeting canonical TGF-β1 or Wnt/β-catenin signaling, or the renin-angiotensin system." (PMID 31024315, 2019). "Klotho, an anti-aging protein, is an emerging target of renal fibrosis progression." (PMID 29590173, 2018). "In our study, urinary hydroxiproline was increased in ZO rats from two 2 months old, although our data demonstrate that the excretion of Klotho, GluAp, and AlaAp activities at 2 and 5 months old correlate better than hydroxyproline even with renal fibrosis or renal hydroxyproline content." (PMID 30483154, 2018). "While Rhein treatment effectively reduced renal fibrosis severity and improved the protein expressions in control siRNA-injected mouse kidney, the anti-renal fibrotic effects of Rhein were largely abolished when Klotho was knocked down." (PMID 27703201, 2016). "Therefore our studies demonstrate that Rhein retention of Klotho through an epigenetic mechanism contributes to its anti-renal fibrosis functions." (PMID 27703201, 2016). "Lastly, the renoprotective anti-aging factor klotho, which is involved in a myriad of homeostatic processes, might mitigate renal fibrosis by suppressing TGF-β signaling and vice versa, deficient klotho expression may accelerate senescence and fibrosis." (PMID 26380262, 2015). "In addition, a previous study revealed that klotho suppressed renal fibrosis by inhibiting Wnt signaling in a model of kidney obstruction." (PMID 25695625, 2015). "Whereas Klotho depletion resulted in increased renal fibrosis, Klotho replacement therapy significantly alleviated the pathology, suggesting that decreased Klotho levels may contribute to the pathogenesis of renal fibrosis." (PMID 24987372, 2014). "Moreover, administration of indoxyl sulfate to 5/6-nephrectomized rats accelerated the development of renal fibrosis, and its administration to hypertensive rats reduced the expression of klotho and promoted cell senescence accompanied by renal fibrosis." (PMID 22069747, 2011). "Therefore, Bolstering Klotho levels, either pharmacologically or through exercise, may thus constitute a novel therapeutic strategy to protect and/or delay the progression of renal fibrosis." (PMID 39325739, 2024). "In addition, Klotho may be an attractive new therapy to mimic the ameliorative effects of aerobic exercise on ageing-induced renal fibrosis." (PMID 39325739, 2024). "In addition, HDAC3 inhibited the expression of klotho by recruiting NCoR and NF-κB to form a complex that acts on the klotho promoter, thereby promoting the progression of renal fibrosis, developing a pro-fibrotic pathway initiated by TGF-β with HDAC3 as an intermediary." (PMID 36148005, 2022). "Additionally, Klotho was reported to suppress pulmonary and renal fibrosis." (PMID 35884879, 2022).
renal fibrosis (continued). "Thus, Klotho is a critical negative regulator of canonical Wnt signaling and suppresses renal fibrosis in the obstructed kidney model by simultaneously suppressing multiple growth factor signaling pathways such as fibroblast growth factor-2 (FGF-2), Wnt, and TGF-β1." (PMID 34483931, 2021). "Interestingly, the restoration of Klotho levels in rodent animals through the administration of soluble Klotho, or the activation of endogenous protein, for instance, promotes the reduction of renal fibrosis, EMT and a decrease in oxidative stress and the inflammatory burden." (PMID 35056905, 2021). "In addition, Klotho supplementation could inhibit renal fibrosis by suppressing the endoplasmic reticulum stress and epithelial-mesenchymal transition." (PMID 34992536, 2021). "Moreover, miRNA‐34a promotes renal fibrosis by down‐regulating KL in tubular epithelial cells." (PMID 33438362, 2021). "Reports show Klotho could retard age‐related renal fibrosis." (PMID 33463897, 2021). "Similarly, BIX also prevents renal fibrosis by downregulating klotho with decreased H3K9me1." (PMID 31515511, 2020). "Additionally, Klotho inhibits renal fibrosis by antagonizing Wnt/β-catenin signaling." (PMID 32704023, 2020). "However, no human studies have examined the association between soluble klotho and renal fibrosis, and the exact role of soluble klotho in renal fibrosis in humans is unknown." (PMID 29590173, 2018). "In addition to renal fibrosis, it is unclear whether podocyte foot process changes are correlated with soluble klotho level." (PMID 29590173, 2018). "Therefore our results support Klotho as a promising target for anti-renal fibrosis therapies." (PMID 27703201, 2016). "Therefore the klotho gene may reduce the progression of diabetes-induced renal fibrosis by inhibiting ECM and EMT." (PMID 25695625, 2015). "Kl−/− deficient mice with unilateral ureteral obstruction (UUO) had higher TGF-β1 levels and more renal fibrosis than WT wild type mice with UUO in human kidney, decreased Klotho expression occurs in early stages of CKD, and could be responsible for early increase in serum FGF23 level." (PMID 24693499, 2013). "Liu and his colleagues (2017) noticed that Klotho treatment suppressed EMT and correlated renal fibrosis in cyclosporine A rats." (PMID 39276250, 2025). "Regarding fibrosis, it has been reported that the inhibition of CpG methylation in the Klotho gene promoter induces Klotho expression, which subsequently suppresses TGF-β signaling and alleviates renal fibrosis." (PMID 40427517, 2025). "Klotho protein delivery has been demonstrated to inhibit TGF-β activity, thereby protecting against renal fibrosis." (PMID 40004457, 2025). "Collectively, Klotho activation by Vinpo was thought to be responsible for Vinpo’s counteracting effect on β-catenin signaling-induced renal EMT-associated TIF and G2/M arrest and might be speculated as a mechanism for its beneficial influence on renal fibrosis." (PMID 39276250, 2025). "Dihydromyricetin administration effectively counteracted the aberrant elevation of miR-34a expression and the reduction of Klotho in UUO kidneys, resulting in notable amelioration of renal fibrosis." (PMID 39325739, 2024). "Klotho (KLO) is an anti-fibrotic protein expressed in the kidneys and has been decreasing in the development of renal fibrosis (RF)." (PMID 39450151, 2024). "Class IIa HDAC inhibitor MC1568 inhibits EMT-mediated renal fibrosis by inhibiting the activation of TGF-β/SMAD3 and the NF-κb signaling pathway, and upregulating the expression of BMP-7, KLOTHO protein." (PMID 38929505, 2024).
renal fibrosis (continued). "This cascade led to a decline in Klotho expression, further amplifying TGF-β1 expression and promoting the progression of renal fibrosis, thereby engendering a positive feedback loop consistent with the pathological cycle of the disease." (PMID 39325739, 2024). "HDAC8, identified as upregulated in the UUO model, is a promoter of renal fibrosis by influencing EMT-related pathways, inducing cell cycle arrest and suppressing the expression of BMP-7 and KLOTHO proteins." (PMID 38929505, 2024). "In other words, low levels of klotho can activate the TGF-β1 signaling pathway, which contributes to diabetes-related renal fibrosis." (PMID 37143722, 2023). "In UUO-induced renal fibrosis model, TGF-β1 induces G9a expression via Smad3 activation, and BIX01294 inhibits G9a-mediated H3K9me1 and attenuates renal fibrosis and retains klotho expression." (PMID 35559246, 2022). "GZ667161 treatment prevented downregulation of klotho in CKD and ameliorated renal fibrosis in 5/6-nephrectomized remnant kidney tissues as shown by Col-I, Col-III, and trichrome staining." (PMID 35660779, 2022). "The relationship between Klotho and CKD was well reported by genetic studies, which was explained by renal fibrosis, inflammation, and the vascular calcification." (PMID 36276390, 2022). "The authors concluded that Klotho inhibited TGF-β and tumor necrosis factor (TNF) signaling, to decrease renal fibrosis." (PMID 35903083, 2022). "Experiments also indicated that Klotho supplementation can prevent and slow down CKD progression, attenuating the characteristic renal fibrosis in CKD." (PMID 35056905, 2021). "When it comes to soluble Klotho, it has been observed, in mice with UUO-induced renal fibrosis, its binding to TGF-β type-II receptor and inhibition of TGF-β1 binding to cell surface receptors as a consequence." (PMID 35056905, 2021). "We think that the protection of Klotho on CKD and renal fibrosis would be more related to its inhibitory effects on cellular senescence." (PMID 33463897, 2021). "It has been reported that TGF-β1 promoted renal fibrosis through inducing EMT in RTECs, and this was partially through inhibiting Klotho expression." (PMID 32571212, 2020). "Here, we observed that Klotho significantly inhibits the activation of β‐catenin and RAS activity, protects mitochondrial functions, and mitigates renal fibrosis." (PMID 31318148, 2019). "Renal fibrosis induced by IS and pCS was found in a mild CKD model together with DNA hypermethylation of the Klotho gene and reduced renal Klotho mRNA and protein expression." (PMID 30200452, 2018). "In vitro and in vivo experiments have demonstrated that reduced renal expression of klotho enhanced the activity of transforming growth factor-β1 (TGF-β1) and aggravated renal fibrosis by unilateral ureteral obstruction in mice." (PMID 25695625, 2015). "By contrast, overexpression of klotho has been shown to inhibit TGF-β1 signaling and suppress renal fibrosis." (PMID 25695625, 2015). "Klotho also inhibits transforming growth factor-β1 (TGF-β1) signaling and suppresses renal fibrosis and cancer metastasis in mice." (PMID 23516476, 2013). "A recent report demonstrates that Klotho blocks TGF-ß-induced profibrotic signaling by direct interaction with TGF-ß RII and thus ameliorates renal fibrosis." (PMID 23724005, 2013). "Klotho is an essential negative regulator of canonical WNT/β-catenin signaling as Klotho’s extracellular domain suppresses WNT/β-catenin signaling by interacting with numerous WNT ligands and inhibits renal fibrosis." (PMID 40514411, 2025). "Similarly, in rats with unilateral ureteral obstruction, ginsenoside Rg1 inhibits TGF-β1-induced Smad3 phosphorylation while restoring Klotho and Smad7 expression, which collectively attenuate EMT and renal fibrosis." (PMID 41415561, 2025).